MMP19 (matrix metallopeptidase 19)
Diseases named in the same sentence as MMP19 in open-access papers (continued):
Sharing a sentence is not in itself a finding about the gene and the disease.
myocardial infarction (4 papers, 2022). Gross necrosis of the myocardium, as a result of interruption of the blood supply to the area, as in coronary thrombosis. "In a myocardial infarction model, miR-486-5p reduced the production of MMP19 in fibroblasts, reducing the cleavage of VEGF-A and therefore promoting angiogenesis and cardiac repair." (PMID 36153544, 2022).
rheumatoid arthritis (4 papers, 2006 to 2025). A chronic, systemic autoimmune disorder characterized by inflammation in the synovial membranes and articular surfaces. "Matrix metalloproteinase-19 (MMP-19) was originally isolated from the inflamed synovium of a rheumatoid arthritis patient, from mammary gland, and liver." (PMID 21787393, 2011). "MMP19 was originally isolated from a rheumatoid arthritis patient." (PMID 40006985, 2025). "Among the unclassified MMPs, MMP-19 is used as a T-cell–derived autoantigen from patients with rheumatoid arthritis, but its exact function is not fully characterized." (PMID 35444067, 2022). "Biochemical and physiological roles of MMP-19 have not been characterized, although MMP-19 is used as a T-cell–derived autoantigen from patients with rheumatoid arthritis." (PMID 35444067, 2022).
colitis (3 papers, 2021 to 2022). Inflammation of the colon. "In a DDS-induced model of colitis, MMP-19−/− mice show increased susceptibility and exacerbation of colitis reflected by a reduced survival rate, severe tissue destruction, increased levels of colonic and a plasmatic level of proinflammatory modulators and failure to resolve inflammation." (PMID 33802197, 2021). "MMP-19 coordinates the appropriate innate immune response in colitis, which is critical to balancing the host response to colon pathogens." (PMID 36776395, 2022). "The protective effect of MMP-19 over colitis seems to originate from its capacity to control neutrophils and macrophage migration to wounded mucosa, possibly through the processing of the chemokine domain of fractalkine (CX3CL1)." (PMID 33802197, 2021). "MMP19, a member of the MMP protein family, is involved in maintaining the epithelial barrier of the colon and attenuating colitis development." (PMID 36550414, 2022).
COVID-19 (3 papers, 2021 to 2024). A disease caused by infection with severe acute respiratory syndrome coronavirus 2. "Whereas data on MMP-19 in COVID-19 are scarce, it has been related to enhanced fibrogenesis in pulmonary tissue." (PMID 38957465, 2024). "However, the human MMP family consists of several genes, and herein we show increased transcript levels of MMP-19, MMP-23B and MMP-25 in relation to disease severity in PBMC from COVID-19 patients, underscoring a role for MMPs beyond that of MMP-9 in COVID-19." (PMID 38957465, 2024).
gastric cancer (3 papers, 2022 to 2024). A primary or metastatic malignant neoplasm involving the stomach. "Shen D et.al studied hsa_circ_0005556/miR-4270/MMP19 axis and revealed that this axis was involved in proliferation, migration, and invasion of gastric cancer." (PMID 38200573, 2024). "Circ_0005556, a circular RNA, sponged miR-4270, resulting in MMP19 overexpression, and subsequent proliferation, migration and invasion of gastric cancer cells." (PMID 37719019, 2023). "It has also been reported that circERBB2 facilitated the progression of gastric cancer via miR-503/CACUL1 and miR-637/MMP-19 signaling." (PMID 35931993, 2022).
lung carcinoma (3 papers, 2022 to 2024). "As for its clinical application for lung cancer diagnosis and treatment, MMP19 has been reported to promote the metastasis of lung cancer and is associated with increased mortality of lung cancer as an active biomarker." (PMID 35155435, 2022). "Genes MMP16 (ENSP00000286614) and MMP19 (ENSP00000313437) belong to the matrix metalloproteinase family that is associated with multiple cancer subtypes, including lung cancer." (PMID 35155435, 2022).
nasopharyngeal carcinoma (3 papers, 2019 to 2021). A carcinoma arising from the nasopharyngeal epithelium. "The low expression of MMP19 can promote the deterioration and growth of some tumors, such as nasopharyngeal carcinoma." (PMID 35069702, 2021).
thyroid cancer (3 papers, 2019 to 2024). "For example, the combined signal of MMP11 and MMP19, which both cleave aggrecan and gelatin, resulted in a larger area under the curve (AUC) value than individually in thyroid cancer." (PMID 39239548, 2024). "The combined signal of MMP11 and MMP19, both of which cleave aggrecan and gelatin, resulted in a higher AUC value than individually in thyroid cancer." (PMID 31200666, 2019). "For example, for thyroid cancer (THCA), MMP11 showed an AUC of 0.928 alone, but when combined with MMP19, multivariate analysis showed an AUC of 0.961." (PMID 31200666, 2019).
colon cancer (2 papers, 2021 to 2023). "The levels of MMPs including MMP-2, MMP-9, MMP-11, and MMP-19 are elevated in the colon cancer patients as compared to normal individuals." (PMID 34096454, 2021).
Obesity (2 papers, 2023 to 2024). Accumulation of substantial excess body fat. "Metalloproteinases, particularly MMP2, MMP9, and MMP19, regulate the extracellular matrix, which is crucial in multifactorial conditions like obesity and related diseases." (PMID 39683581, 2024). "The molecular mechanisms at play remain poorly defined, and other studies are required to determine precisely the role of MMP19 in adipocyte-SVF cells crosstalk during obesity." (PMID 37445827, 2023). "Paradoxically, MMP19 was shown to be markedly induced in later stages of adipocyte differentiation and in adipose tissue of mouse models of obesity." (PMID 37445827, 2023). "One explanation could be that MMP19 may negatively control adipogenesis and the increased expression in obesity may be a way of limiting further weight gain." (PMID 37445827, 2023). "Moreover, MMP19 was identified, among other MMPs, by microarray analysis to be robustly upregulated in human adipocytes treated for 4 h or 24 h with macrophage-conditioned medium, suggesting a paracrine regulatory role of MMP19 during adipose tissue expansion in obesity." (PMID 37445827, 2023). "However, in two animal models of genetic obesity (ob/ob and db/db) and in a HFD model, while mRNA levels for MMP2, MMP3, MMP12, MMP14, MMP19, and TIMP1 are robustly induced, MMP7 (and MMP3) transcripts are markedly reduced in obese visceral adipose tissue compared to lean tissue." (PMID 37445827, 2023).
Stroke (2 papers, 2022 to 2025). Sudden impairment of blood flow to a part of the brain due to occlusion or rupture of an artery to the brain. "PPARα KO brains had upregulated expression of several genes already implicated in neural injury following stroke such as Mmp19, Il6, Saa3, and Il1r2." (PMID 40362325, 2025). "The most significantly upregulated genes, including Lpl, Spp1, Cd36, Mmp2, and Mmp19, and the most highly enriched genes, including Cd5l, Mmp3, Mmp12, and Mmp13, indicate a pronounced disturbance in lipid homeostasis in infarcts at 7 weeks after stroke." (PMID 34819339, 2022).
acute aortic dissection (1 paper, 2013). "They found a number of matrix metalloproteases (MMP-19, MMP-12, MMP-9) were differentially expressed in acute aortic dissection patients." (PMID 23642232, 2013).
Arthritis (1 paper, 2019). Inflammation of a joint. "Among these DEGs are MMP1 and MMP19, which are proteins linked to the breakdown of extracellular matrix (ECM) in normal physiological (embryonic development, reproduction, and tissue remodeling) and disease processes (arthritis, cancer metastasis, and HIV pathogenesis)." (PMID 31484431, 2019).
asthma (1 paper, 2012). "The role of MMP-19 appears to be prominent in cell types or in compartments where these substrates as well as MMP-19 are simultaneously available, as was documented in the study showing that MMP-19-deficiency causes an accumulation of tenascin-C in bronchial walls of mice suffering from asthma." (PMID 23056273, 2012).
Burkitt lymphoma (1 paper, 2024). A rare form of malignant mature B-cell non-Hodgkin lymphoma. "MMP19 was highly expressed in adipocytes, heart, liver, and Burkitt’s lymphoma cells (Raji cells), and PLXDC1 was highly expressed in CD4+ T cells, CD56+ NK cells, CD8+ T cells, thymus cells and pineal cells." (PMID 39118664, 2024).
cerebral amyloid angiopathy (1 paper, 2020). "Our study identified overexpression of MMP19 that was previously associated with cerebral amyloid angiopathy, which is one of the active processes commonly found in the AD progress." (PMID 32872134, 2020).
cholangiocarcinoma (1 paper, 2020). A carcinoma that arises from the intrahepatic biliary tree (intrahepatic cholangiocarcinoma) or from the junction, or adjacent to the junction, of the right and left hepatic ducts (hilar cholangiocarcinoma). "In contrast, mononuclear phagocytes exhibited up‐regulation of chemokines such as CCL4, CCL4L2, and CCL3L3 in the cholangiocarcinoma samples and extracellular remodeling genes such as MMP19, MMP12, and HS3ST2 in the metastatic patients." (PMID 33332768, 2020).
epilepsy (1 paper, 2016). A brain disorder characterized by episodes of abnormally increased neuronal discharge resulting in transient episodes of sensory or motor neurological dysfunction, or psychic dysfunction. "Inhibition of MMP19 and other matrix metalloproteinases may prevent development of epilepsy at the early stage of epileptogenesis." (PMID 27903967, 2016).
gallbladder carcinoma (1 paper, 2023). "In gallbladder carcinoma (GBC), MMP19 can stabilize the epithelial–mesenchymal transition (EMT) by increasing Axl expression." (PMID 37246211, 2023).
head and neck cancer (1 paper, 2020). A primary or metastatic malignant neoplasm affecting the head and neck. "Expression levels of MMP10, MMP19, MMP24, and MMP25 were associated with prognosis in TCGA cohort of head and neck cancer by Kaplan-Meier analysis." (PMID 32850314, 2020). "Expression levels of MMP10, MMP19, MMP24, and MMP25, which were associated with prognosis in head and neck cancer, were identified using Kaplan–Meier method and log-rank test." (PMID 32850314, 2020).
idiopathic pulmonary fibrosis (1 paper, 2013). Idiopathic pulmonary fibrosis (IPF) is a nonneoplastic pulmonary disease that is characterized by the formation of scar tissue within the lungs in the absence of any known cause. "Matrix metalloproteinase (MMP) 7, osteopontin, Twist1, and MMP19, are among suggested mediators identified using this strategy in idiopathic pulmonary fibrosis (IPF), a disease characterised by a histological pattern of usual interstitial pneumonia (UIP)." (PMID 23915349, 2013).
injury (1 paper, 2012). Damage inflicted on the body as the direct or indirect result of an external force, with or without disruption of structural continuity. "In the present study, MMP-19-deficient mice showed resistance to chronic liver injury caused by CCl4 intoxication and recovered faster than WT animals upon removal of the toxin." (PMID 23056273, 2012).
invasive carcinoma (1 paper, 2022). A carcinoma that is not confined to the epithelium, and has spread to the surrounding stroma. "Matrix metalloproteinase 19 (Mmp-19) is an inhibitor of angiogenesis whose expression is downregulated in invasive carcinomas." (PMID 35731367, 2022).
lymph node metastases (1 paper, 2019). "Ectopic MMP19 expression was positively associated with lymph node metastases (P = 0.029), intramural vascular invasion (P = 0.015) and serum carcinoembryonic antigen levels (P = 0.045)." (PMID 31088409, 2019). "High MMP19 expression was significantly correlated with lymph node metastases (P = 0.029), intramural vascular invasion (P = 0.015) and serum carcinoembryonic antigen status (P = 0.045)." (PMID 31088409, 2019). "High MMP19 expression was significantly correlated with lymph node metastases and intramural vascular invasion, which suggests that MMP19 may play a critical role in CRC invasion and metastases." (PMID 31088409, 2019).
metastatic cancer (1 paper, 2024). A carcinoma which has spread from the original site of growth to another anatomic site. "Meantime, MMP19 expression, or p-STAT3 and Ack-STAT3 of lung metastatic cancer tissues in the corresponding groups were also declined." (PMID 38560562, 2024).
mild cognitive impairment (1 paper, 2024). "MMP19 has been found to be associated with neurodegenerative processes and related pathways, is one of the differential genes for early and late mild cognitive impairment." (PMID 39228516, 2024).
Oral ulcer (1 paper, 2016). Erosion of the mucous mebrane of the mouth with local excavation of the surface, resulting from the sloughing of inflammatory necrotic tissue. "The expression levels of IL-4, MMP-19, and Activin A are closely related to the occurrence of oral ulcers." (PMID 27375764, 2016).
Sepsis (1 paper, 2023). Sepsis is defined as life-threatening organ dysfunction caused by a dysregulated host response to infection. "Our study specifically highlights the differential expression of matrix metalloproteinases (MMPs), such as Mmp2-3, Mmp8-9, Mmp14, Mmp17, Mmp19, and Mmp28-29, with significantly higher expression in LPS-induced sepsis compared to CLP-induced sepsis." (PMID 37510271, 2023).
skin tumors (1 paper, 2008). "Pendas and colleagues studied functions of MMP19 in metabolism, carcinogenesis, and angiogenesis and showed that MMP19-deficient mice are more susceptible for skin tumors and exhibit earlier tumor angiogenesis." (PMID 18523579, 2008).
synovitis (1 paper, 2021). Inflammation of a synovial membrane. "In sum, this study indicated that WB had obvious inhibitory effects on synovitis of CIA rats, and the mechanisms of which may be involved in downregulating the expression levels of several key proteins including MMP3, MMP19, LBP, IRAK4, and ARPC5." (PMID 34708132, 2021).
tumor (52 papers, 2006 to 2026). "We discover a novel subtype of tumor-associated macrophages (TAMs) that are positive both for matrix metalloproteinase 19 (MMP19) and receptor activator of nuclear factor-κB (RANK) expression (MMP19+ RANK+ TAMs)." (PMID 41362730, 2026). "Mmp-19-deficient mice display earlier onset tumor angiogenesis and Mmp-19 reduces endothelial cell angiogenesis by proteolytic cleavage of plasminogen, generating angiostatin-like fragments as endogenous angiogenesis inhibitors." (PMID 35731367, 2022). "In contrast, the MMP-19-deficient mice showed decreased tumor angiogenesis and invasion pointing, thus, to a potential dual role of MMP-19." (PMID 21787393, 2011). "Notably, MMP19, which is expressed in the tumor-invasive fronts, has been implicated in facilitating the invasiveness of HNSCC." (PMID 38778403, 2024). "In addition, their analysis showed that the upregulation of MMP11, MMP14, MMP17, and MMP19 is significantly associated with a more advanced tumor stage and a worse long-term prognosis." (PMID 37511338, 2023). "Also, in the clinicopathological and prognosis analyses, upregulated MMP11, MMP14, MMP17, and MMP19 were significantly associated with a higher tumor stage and a worse prognosis." (PMID 34804973, 2021). "The interaction between bone metastatic BC tumor cells and MMP19+ TAMs was mediated by the amyloid precursor protein (APP) signaling pathway." (PMID 41362730, 2026). "Comprehensive analysis of ligand-receptor interactions in the cell communications among tumor cells, MMP19+ TAMs and CD8+ T cell subsets was conducted." (PMID 41362730, 2026). "MMP19+ RANK+ TAMs are organized in a ring-like arrangement surrounding the tumor nests, constructing a barrier structure that impedes the infiltration of CD8+ T cells into the tumor core in LC-BoM." (PMID 41362730, 2026). "In cancer, MMP-19 promotes tumor progression in gallbladder carcinoma, colorectal cancer, and NSCLC but exhibits tumor-suppressive activity in nasopharyngeal carcinoma." (PMID 41281748, 2025). "AHCY-deficient SW480 cells exhibit significant upregulation of genes important for the tumor microenvironment pathway, such as MMP19, MMP24, and CSF2, as well as upregulated activation of PLAU and BCL2." (PMID 38003292, 2023). "Significant changes have been detected in the tumor microenvironment pathway including genes MMP19, MMP24, and CSF2, as well as PLAU, BCL2, TIAM1 and Rac1." (PMID 38003292, 2023). "Our results indicated that, of the selective 10 tumor-promoting genes of TAMs, only MMP19, and SIRPα can predict ICB response in ICC patients." (PMID 36158683, 2022). "MMP19, as a member of the MMPs family, had been reported to promote tumor growth, invasion, metastasis and chemoresistance." (PMID 35729639, 2022). "MMP11, MMP14, MMP16, MMP17, MMP19, and MMP23b were positively correlated with the tumor stage, that is, the mRNA levels of MMPs in patients with higher tumor stage were always high." (PMID 34804973, 2021). "In the clinicopathological analyses, upregulated MMP11, MMP14, MMP16, MMP17, MMP19, and MMP23B were significantly associated with a higher tumor stage." (PMID 34804973, 2021). "Our results warrant further studies on the detailed mechanisms by which MMP19 facilitates tumor progression in CRC." (PMID 31088409, 2019). "In oropharyngeal squamous cell carcinoma, expression of MMP-19 is observed in healthy tissue areas, non-invasive tumor parts and also tumor invasive front, but its expression is absent in neoplastic regions." (PMID 24531055, 2014). "MMP-19 was also shown to exhibit an anti-tumor effect as it suppresses tumor angiogenesis and invasion." (PMID 23056273, 2012). "Titz and colleagues treated tumor extracellular matrix with recombinant MMP-19 and analyzed its effect on capillary like formation." (PMID 16824202, 2006).